KRTAP6-2 (keratin associated protein 6-2)
Description:
In the hair cortex, hair keratin intermediate filaments are embedded in an interfilamentous matrix, consisting of hair keratin-associated proteins (KRTAP), which are essential for the formation of a rigid and resistant hair shaft through their extensive disulfide bond cross-linking with abundant cysteine residues of hair keratins. The matrix proteins include the high-sulfur and high-glycine-tyrosine keratins.
Synonyms: KAP6.2
Tractability: No criterion of Open Targets' tractability assessment is met for any kind of drug.
Gene: Protein-coding gene on chromosome 21 (30,598,590 to 30,598,902, reverse strand). Ensembl gene ENSG00000186930.
Pathways (Reactome):
Developmental Biology: Keratinization
Gene Ontology:
Molecular function: identical protein binding; protein binding
Biological process: keratinization
Cellular component: cytosol
Genetic constraint (gnomAD): Loss-of-function variants: 3 observed, 0.81 expected, observed/expected ratio (o/e) 3.7. That is too few expected variants to judge how well the gene tolerates losing a copy. Missense variants: 40 observed, 38.09 expected, observed/expected ratio (o/e) 1.05, 90% interval 0.81 to 1.37. Synonymous variants: 19 observed, 17.8 expected, observed/expected ratio (o/e) 1.07, 90% interval 0.74 to 1.56.
Homologues: Orthologues: chimpanzee KRTAP6-2 (95% identical), pig KRTAP6-2 (63% identical).